MYC (MYC proto-oncogene, bHLH transcription factor)
Diseases named in the same sentence as MYC in open-access papers (continued):
Sharing a sentence is not in itself a finding about the gene and the disease.
tumor (continued). "Transcriptional dysregulation due to alterations in KRAS and MYC affects initiation, development, and survival of this tumor type." (PMID 37831776, 2023). "In colorectal cancer, METTL3 cooperates with IGF2BP2 to increase the stability of SOX2 RNA, which promotes the transcription of MYC and enhances the self-renewal and proliferation of tumor cells." (PMID 37996892, 2023). "Over time, increasing numbers of researchers have realized that MYC can drive tumor immunosuppression by interacting with other molecules in the TME." (PMID 36966168, 2023). "Peptides, nucleic acids, or other drug molecules that do not pass the cellular barrier require specific formulations for appropriate and selective delivery into MYC-dependent tumor cells." (PMID 36969025, 2023). "The MYC gene is frequently altered in >30% of human malignancies, spanning a wide spectrum of tumor subtypes." (PMID 37047552, 2023). "Therapeutic planning and response monitoring of MYC-amplified MB are currently based on imaging techniques, which are necessary to monitor tumor size and most importantly provide information about anatomical location and metastases." (PMID 37173990, 2023). "By focusing on the pivotal gene c-MYC, we have designed and synthesized a novel series of compounds, demonstrating high anti-tumor activity and selectivity in preliminary experiments." (PMID 38275631, 2023). "The inclusion of the tTA-Tet-OFF system allowed us to investigate the effect of MYC suppression on tumor maintenance through the administration of doxycycline (dox) into the diet of these mice." (PMID 36869047, 2023). "JQ1 releases BRD4 from chromatin and reduces MYC transcription and tumor growth in endometrial and ovarian cancers." (PMID 36969025, 2023). "MYC was highly expressed throughout virtually all tumor cells, confirming functional TRE-MYC activity in GMYC tumors." (PMID 36869047, 2023). "Most of these studies exploited a variety of transformed and tumor cell lines to explore pathologic MYC function." (PMID 37941901, 2023). "Inhibitors against CDK7 and CDK9 demonstrate potent anti-tumor effects in MYC-driven cancers, including T cell acute lymphoblastic leukemia, mixed-lineage leukemia, neuroblastomas and small cell lung cancers." (PMID 37755397, 2023). "MYC regulates tumor proliferation, metastasis, and metabolism through signaling pathways such as the AKT/mTOR pathway." (PMID 37122373, 2023). "Here, we performed a detailed mechanistic study using the dual approaches of inducible genetic KD and pharmacologic inhibition of STAT3 on MYC gene regulation, MB tumor growth and chemosensitivity." (PMID 37190167, 2023). "They demonstrated that HPV16 DNA integrates into the chromosome band 8q24.21 at the MYC locus and observed MYC amplification (8–12 copies) in both the IC2 tumor and in the cell line, and in the case of the latter, MYC was overexpressed (3.4-fold)." (PMID 37375112, 2023). "c-MYC upstream regulatory elements such as enhancers and super-enhancers that are located at MYC-515 regulate the transcription of c-MYC gene in a tissue or tumor type-specific manner." (PMID 37025163, 2023). "More recently, novel studies have shown that MYC plays a role in tumorigenesis in cell intrinsic signaling and has a broader spectrum of functions in the tumor microenvironment." (PMID 37755397, 2023). "As an essential component of lipid rafts in mammalian cells, cholesterol is involved in many oncogenic signaling pathways in tumor cells, including MYC, MAPK and Wnt pathway." (PMID 37938654, 2023). "MYC activation and PTEN loss of function added to mutations to DNA repair genes such as BRCA2 create instability to the genome and cause tumor heterogeneity and progression." (PMID 37175453, 2023).
tumor (continued). "MYC therefore activates biosynthetic processes that enhance the expression of MAA II-binding sialoglycans on the tumor cell surface." (PMID 36897988, 2023). "Since most tumor cells rely on continuous MYC expression, it is plausible that mRNA destabilization by short interfering RNAs (siRNAs) causes inhibition of cell proliferation and tumor regression." (PMID 36969025, 2023). "Here, we use bioinformatics to identify a splicing event in another proto-oncogene, HRAS, that is regulated by MYC across multiple tumor types." (PMID 37399401, 2023). "Recently, it has been found that expression changes of both tumor-type-specific and pan-cancer splicing factors (comprising hubs of SRSF2/3/7) modules are frequently associated with MYC activity in several cancer types." (PMID 37443779, 2023). "ODC1 activity is frequently elevated in cancer through deregulation of MYC, resulting in higher polyamine content to support rapid tumor cell proliferation." (PMID 36845724, 2023). "MYC has emerged as a master regulator governing tumor intrinsic and tumor microenvironment interactions, supporting tumor progression and driving drug resistance." (PMID 37755397, 2023). "Using a conditional transgenic model of MYC-induced tumorigenesis, we find that MYC drives the display of a particular glycan known as disialyl-T on tumor cells." (PMID 36897988, 2023). "Screening of a database of FDA (Food and Drug Administration)-approved drugs shows Polymyxin B displays high binding affinity for SCARB2 protein, disrupts the SCARB2-MYC interaction, decreases MYC activity, and reduces the tumor burden." (PMID 37739936, 2023). "SCARB2 knockout suppressed the proliferation, invasion and tumor initiation efficiency of HCC cells by reducing MYC transcriptional activity and acetylation." (PMID 37739936, 2023). "The depletion of arginine using pegylated arginine deiminase (ADI-PEG20) significantly suppresses tumor growth and enhances the survival of mice, specifically in MYC-driven tumors." (PMID 38203275, 2023). "Unfortunately, all our analyzed patients suffered from continuous tumor burden during the time span where CSF samples were collected, reflecting the deleterious nature of MYC-amplified MB." (PMID 37173990, 2023). "The MYC inhibitor MYC361i synergized with vincristine to reduce tumor growth and stem-like cells in a zebrafish model of RMS." (PMID 37345125, 2023). "Here, we demonstrate that C.B reprograms the proliferation, migration, stemness, and tumor growth in CRC by regulating pivotal signal molecules including MYC." (PMID 36941257, 2023). "In the TCGA database, the expression levels of HAT1 and SLC39A7 in tumor tissues were higher than those in adjacent normal tissues, while the expression level of MYC in tumor tissues was lower than that in adjacent normal tissues." (PMID 37000317, 2023). "Several genes involved in tumorigenesis and tumor progression were similarly found to be activated by SEs in cancer, notably MYC." (PMID 37415185, 2023). "Here, we briefly discuss multiple immune-related functions of MYC in the tumor immune environment and some recent research progress." (PMID 36966168, 2023). "In conclusion, MYC plays a significant role in the biological process of tumor cells by promoting glycolysis, glutamine decomposition, nucleotide synthesis, fatty acid metabolism and other pathways to promote the proliferation of tumor cells." (PMID 36994237, 2023).
tumor (continued). "MYC mandates tumor cell fate and orchestrates changes in the tumor microenvironment, including the activation of angiogenesis and suppression of the host immune response." (PMID 36770824, 2023). "For instance, miR-21 is an oncogenic miRNA that targets tumor suppressor genes such as PTEN and PDCD4, while miR-34a is a tumor suppressor miRNA that targets oncogenes such as MYC and BCL2." (PMID 37460924, 2023). "Collectively, our findings indicate that KDM4B promotes tumor progression through the miR-181d-5p/SCFFBXL3+CRY2/MYC axis." (PMID 38093312, 2023). "PVT1’s normal expression is monoallelic, and as its promoter competes with the MYC promoter for intragenic PVT1 enhancers on its single expressed allele, in doing so, it acts as a tumor suppressor by regulating the release of MYC transcriptional pausing." (PMID 37444543, 2023). "In vivo study revealed DPYSL3 knockdown in UC tumours significantly suppressed the growth of tumours and decreased MYC and GLUT1 protein expression." (PMID 37380971, 2023). "Quantitative analysis of MSI2 and MYC staining showed that tumor regions of human HCC tissue sections had significantly higher levels of MYC and MSI2, which was consistent with TCGA data regarding MYC and MSI2 mRNA levels." (PMID 37117191, 2023). "In vivo, MYC-targeting via epigenomic programming led to a decrease in tumor size in multiple murine xenograft models." (PMID 36631803, 2023). "These unique findings offer a fresh perspective regarding the significance of MYC oncoprotein regulation in mediating responses to metabolic agents in G3 MB tumor cells." (PMID 37130865, 2023). "CTDNEP1-deficiency-induced tumors resemble the histopathological, transcriptomic, and clinical features of human G3 MB counterparts, suggesting that CTDNEP1 is a potent tumor suppressor in the highly aggressive MYC-driven G3 MBs." (PMID 36765089, 2023). "CHK1 inhibition has been demonstrated in MYC driven tumours and in cancers of heightened replicative stress." (PMID 38214010, 2023). "We next developed a regulatable model to in detail explore the de novo effects of MYC on previously formed GTML tumor cells in vitro." (PMID 36869047, 2023). "In summary, the findings indicate that combined anti–PD-L1 and AFP immunization increased activated CD8+ T cells, including AFP499+ CTLs, inducing the dramatic inhibition of most tumor lesions in c-MYC/Mcl1 mice." (PMID 37040183, 2023). "The mechanisms by which MYC activation promotes tumor progression mainly involve cell proliferation, cell invasion, metabolic reprogramming, genomic instability, angiogenesis, and immune evasion." (PMID 37799727, 2023). "The selective inhibition of CDK1 by small-molecule inhibitors, purvalanol or roscovitine, causes the suppression of the apoptosis protein BIRC5 (survivin), which is essential for the survival of MYC-driven tumor cells." (PMID 37443779, 2023). "Then, the increased c-MYC binds to E-boxes of target genes to command them, enabling the cells to grow and divide persistently, thus initiating the neoplasia formation." (PMID 37025163, 2023). "Among them, the MYC+MEL subcluster exhibited functional enrichment in mesenchymal-like malignant clusters in CM, which are closely associated with tumor invasion and metastasis." (PMID 38065972, 2023).
tumor (continued). "The activation of the inhibitor of differentiation or DNA binding 1 (ID1)/MYC signal promoted immune escape and tumor progression of drug-resistant HCC through PD-L1 up-regulation and CCL5-induced PMN-MDSC recruitment in HCC cells." (PMID 38155974, 2023). "The pro-oncogenic pathways, including E2F, G2M checkpoint and MYC targets pathway, favor tumor cells to promote growth, migration, invasion, and angiogenesis." (PMID 37063853, 2023). "Tumor cells with a cell cycle signature were prevalent in treatment-naive patients, whereas those with MYC/inflammatory signatures were dominant in progressive disease (PD) states after neoadjuvant chemotherapy or liver metastasis." (PMID 38084922, 2023). "Through the integration of innovative murine models of OS and bioinformatics analysis of human OS data sets, we have identified a likely novel immune-regulatory function of MYC in OS tumor biology." (PMID 37279073, 2023). "The protocol was chosen because the patient was 15 years old and the tumor was characterized by MYC amplification, making it strongly aggressive." (PMID 38037472, 2023). "We first utilized a PDX model with transplantation of KRAS WT amplification lung tumor in NSG mice to determine the influence of alone or concomitant inhibition of HIF1A-As2 and MYC on tumor growth." (PMID 37041291, 2023). "MYC, located in the nucleus, is overexpressed in most human tumors, and it drives tumor development via different signaling pathways and at multiple levels." (PMID 36717782, 2023). "Ppp2r5d-deficient HCCs stained positively for c-MYC, consistent with increased AKT activation in pre-malignant and tumor tissues of Ppp2r5d-deficient mice." (PMID 37627221, 2023). "On the one hand, some studies have shown that MYC can be activated by some cytokines in CAFs, including IL-33 and chemokines, to inhibit tumor immunity." (PMID 36966168, 2023). "Growing evidence suggests that iron-associated proteins, such as ferritin and the proto-oncogene c-MYC, contribute to the growth of malignant tumor cells." (PMID 38001941, 2023). "Patient 4 had low MYC amplification levels in the tumor material of a resected metastasis (first available methylation array); however, there was increased MYC amplification in the autopsy material as assessed by methylation analysis." (PMID 37173990, 2023). "MYC overactivation promotes glycolysis in tumor cells, creating a low-glucose environment that favors Treg generation." (PMID 37755397, 2023). "Primary tumor tissues were stained for MYC by IHC, and the percentage of stained tumor cells was quantified to group patients into MYC-positive and MYC-negative samples." (PMID 37642941, 2023). "An increase of tumor-suppressive let-7 family and miR-34a-5p led to a decrease of MYC and perturbation of mitochondrial function." (PMID 36831498, 2023). "To more broadly assess the association of hnRNPs H and F with MYC, we performed a correlation analysis of the MYC activity score and normalized splicing factor expression across tumor types." (PMID 37399401, 2023). "Synthetic lethal interactions between MYC signaling and small-molecule inhibition involved in cell cycling have been therapeutically addressed to selectively kill tumor cells." (PMID 36969025, 2023). "Mechanistically, LN metastasis required tumor cells to undergo a metabolic shift towards fatty acid metabolism induced by the key transcription factor MITF in MYC+MEL cells." (PMID 38065972, 2023). "MYC-associated factor X dimerization transcription factor 1 (MXD1), a MYC antagonist, is a tumor suppressor and opposes the functions of oncogene MYC." (PMID 37833290, 2023).
tumor (continued). "We delve into the signaling pathways and molecular networks orchestrated by MYC in the context of tumor intrinsic characteristics, such as proliferation, replication stress and DNA repair." (PMID 37755397, 2023). "Suppressing MYC expression or inhibiting its function has been shown to lead to significant tumor regression." (PMID 37759234, 2023). "Combined AFP immunization and anti-PD1 treatment significantly suppress c-MYC/Mcl1 tumor progression." (PMID 37040183, 2023). "To examine the effect of inhibition of MYC and CHEK1 on the growth of human G3 MB tumor cells, we treated MYC-driven D425 MB cells with JQ1 or prexasertib individually or in combination." (PMID 36765089, 2023). "Importantly, inhibition of STAT3 signaling significantly attenuated MB tumor growth in subcutaneous and intracranial orthotopic xenografts, increased the sensitivity of MB tumors to cisplatin, and improved the survival of mice bearing high-risk MYC-amplified tumors." (PMID 37190167, 2023). "The combination of alisertib plus T/CQ resulted in tumor regression, suggesting that reducing c-MYC expression confers sensitivity." (PMID 36719686, 2023). "It has been fully clarified that c-MYC promotes the glycolysis and contributes to tumor progression by up-regulating genes involved in glycolysis pathway and metabolism." (PMID 36969848, 2023). "Previous studies demonstrated that NR4A tumor suppression in AML is closely related to MYC transcriptional repression." (PMID 37735686, 2023). "In exploratory biomarker analyses, focal METamp, RB1 wild-type, MYC diploidy, low circulating tumor DNA (ctDNA) burden at baseline, and early molecular response are associated with better outcomes." (PMID 37944528, 2023). "MYC is amplified and/or overexpressed in tumor cells that are sensitive to eIF4A and RAS pathway inhibitors." (PMID 37384411, 2023). "For example, MYC is a key TF that plays an essential role in cancer cell proliferation and survival and has an impact on tumor progression and therapy resistance." (PMID 37175660, 2023). "Overactivation of MYC in adaptive immune cell subsets mainly reduces the killing effect on the tumor by inhibiting effector T cells, in which MYC regulates the expression of CD47 and PD-L1 in various types of tumor cells." (PMID 36966168, 2023). "The results showed that targeting MYC activation by CRISPR/dCasRx-SINEB2 promotes tumor development and metastasis, but targeting EGFP activation has no significant impact on cell mobility." (PMID 36715335, 2023). "Deubiquitinating enzymes, such as USP28, USP36 and USP7, counteract MYC degradation mediated by FBW7, leading to MYC stabilization and tumor cell proliferation." (PMID 37755397, 2023). "In normal circumstances, MYC expression is highly controlled, but in many cancer cells it is overexpressed, leading to tumor progression." (PMID 36979947, 2023). "MYC promotes immunosuppression and contributes to the recruitment of immunosuppressive cells within the tumor microenvironment." (PMID 37755397, 2023). "T cells engage a very proliferative and biosynthetic metabolism once activated and are likely to engage a similar metabolic adaptation as the MYC-high tumor cells." (PMID 37946084, 2023). "This correlation is also evident in tumor cell-derived gene expression data from MM patients, underscoring MYC’s specific influence on gene expression in MM." (PMID 38067212, 2023). "In particular, MYC activates PD-L1 translation in response to tumor environment changes, allowing for immune evasion, HCC progression, and metastasis formation." (PMID 36902316, 2023).